RERGL (RERG like)
Description:
Binds GDP/GTP and may possess intrinsic GTPase activity.
Synonyms: FLJ22655
Tractability: No criterion of Open Targets' tractability assessment is met for any kind of drug.
Gene: Protein-coding gene on chromosome 12 (18,080,869 to 18,320,107, reverse strand). Ensembl gene ENSG00000111404.
Subcellular location (Human Protein Atlas): Nucleoplasm
Gene Ontology:
Molecular function: GTPase activity; G protein activity; GTP binding
Genetic constraint (gnomAD): Loss-of-function variants: 13 observed, 16.48 expected, observed/expected ratio (o/e) 0.79, 90% interval 0.51 to 1.25. The upper end of that interval is the gene's LOEUF score, 1.25, which puts it in group 5 of 6, group 1 being the genes least tolerant of losing a copy. Missense variants: 200 observed, 191.92 expected, observed/expected ratio (o/e) 1.04, 90% interval 0.93 to 1.17. Synonymous variants: 63 observed, 69.25 expected, observed/expected ratio (o/e) 0.91, 90% interval 0.74 to 1.12.
Homologues: Orthologues: dog RERGL (96% identical), chimpanzee RERGL (93% identical), rabbit RERGL (93% identical), pig RERGL (92% identical), macaque RERGL (90% identical), guinea pig RERGL (89% identical), mouse Rergl (86% identical), rat Rergl (85% identical), zebrafish rergla (65% identical). Paralogues in human: RASL11A (37% identical), RERG (35% identical), RASL11B (33% identical), RASL12 (30% identical), RRAD (30% identical), GEM (28% identical), RAP1A (28% identical), RAP1B (28% identical), RIT1 (28% identical), RAP2A (27% identical), RAP2C (27% identical), REM1 (27% identical), and 23 more.
Diseases named in the same sentence as RERGL in open-access papers:
RERGL is named in the same sentence as 7 diseases in open-access papers, as found by Europe PMC text mining. Sharing a sentence is not in itself a finding about the gene and the disease. The quoted sentences say what the papers report.
acute kidney injury (1 paper, 2025). Sudden and sustained deterioration of the kidney function characterized by decreased glomerular filtration rate, increased serum creatinine or oliguria. "Genes AADACL4 and RERGL, both suppressed by acute kidney injury (AKI) and ABMR, were increased at week 52, also suggesting recovery from injury." (PMID 40301559, 2025).
breast tumors (1 paper, 2015). "Additionally, we assembled a panel of genes exhibiting differences in the frequency of copy number changes between high-grade and low-grade breast tumors groups, including two of those genes here reported (RERGL and HSD17B12)." (PMID 25391423, 2015). "We identified three new focal rearrangements in grade III/LVI-positive breast tumors: 4q13 and 11q11 amplifications (harboring the ADAMTS3 and the HSD17B12 genes, respectively) and a homozygous deletion at 12p12.3 (containing, among others, the RERGL gene)." (PMID 25391423, 2015).
colorectal cancer (1 paper, 2017). A primary or metastatic malignant neoplasm that affects the colon or rectum. "RERG is a negative regulator of cell proliferation that is a close family member of the RERGL gene affected by a rare structural variation of 12p12.3 that increases familial colorectal cancer risk." (PMID 28257124, 2017).
papillary thyroid cancer (1 paper, 2017). "The down-regulated expression of RERGL was related to poor prognosis in papillary thyroid cancer patients, and also implicated with advanced stage EC patients in our study." (PMID 29297280, 2017).
RERGL also shares sentences with these, for which no sentence is quoted: Macrocephaly (1 paper); schizophrenia (1); tumor (1).